DMD (dystrophin)
Diseases named in the same sentence as DMD in open-access papers (continued):
Sharing a sentence is not in itself a finding about the gene and the disease.
muscular dystrophy (continued). "Given that autophagic deficits are complicators of tissue recovery in various neuromuscular disorders, including also muscular dystrophies due to COL6 and DYSF deficiencies, the expansion of the compound’s potential applicability could also reach beyond DMD treatment." (PMID 39859157, 2025). "However, skeletal muscle growth sometimes goes in the opposite direction of muscle hypertrophy because of additional stimuli that reduce dystrophin protein expression or disrupt the balance between muscle protein synthesis and degradation and thus leads to muscular dystrophy and muscle atrophy." (PMID 40034097, 2025). "However, as previously discussed, DMD is a prevalent disorder of muscular dystrophy caused by mutations in the dystrophin gene, rather than neural damage." (PMID 37525241, 2023). "There is no known treatment for dystrophin-associated muscular dystrophies." (PMID 35168641, 2022). "In the group of congenital muscular dystrophies, 11 patients received a genetic diagnosis with mutations in the following genes: LAMA2 (three cases); POMGNT1 (one case); COL6 (one case); TTN (one case); GMPPB (one case); POMT2 (one case); POMGNT2 (one case); DMD (one case); and SCGA (one case)." (PMID 34675869, 2021). "Additionally found to be implicated in dystrophin-deficient muscular dystrophy, H19 has been shown to function in a non-genomic manner by associating and stabilizing dystrophin." (PMID 34436226, 2021). "The nature of an identified dystrophin mutation often affords some clinical insight into prognosis—Duchenne results from complete absence of the dystrophin gene, where the milder “Becker” muscular dystrophy (BMD) results from various partial impairments of dystrophin abundance or function." (PMID 33072932, 2018). "However, there were six individuals with classically pathogenic DMD variants who did not have any signs of latent or undiagnosed muscular dystrophy." (PMID 27446933, 2016). "Therefore, modeling of MTJ assembly and stability in the zebrafish may yield important insights into disease manifestations in patients with myopathies and muscular dystrophies, particularly those that involve the dystrophin-DGC." (PMID 24478725, 2014). "Thus, for a more efficient rescue of muscular dystrophy in patients, therapeutic strategies aiming at a balanced expression of sarcolemmal levels of both, dystrophin and plectin, could prove useful." (PMID 23758845, 2013). "Thus, as this promoter achieved long-term dystrophin expression in the mdx mouse, it might be a candidate promoter for gene therapy of murine muscular dystrophy models." (PMID 21445245, 2011). "Thus, dystrophin from the ESCs is required to correct muscular dystrophy globally." (PMID 19277212, 2009). "The dystrophin-glycoprotein complex (DGC) provides structural integrity to the sarcolemma, and disruption of the DGC leads to muscular dystrophy." (PMID 42234522, 2026). "Given his dysmorphic features, excessive global delays than expected for muscular dystrophy, brain MRI abnormalities, and neuromuscular clinical findings more consistent with BMD than DMD, he returned to the genetics clinic for further evaluation." (PMID 39915227, 2025). "Human dystrophin in DYS-HAC1; DMD-null mice drastically improved muscular dystrophy phenotypes seen in DMD-null mice; however, the proportion of myofibers with central nuclei in DYS-HAC1; DMD-null mice had a tendency to be slightly higher than that in WT mice." (PMID 39805937, 2025). "However, dystrophin, the gene involved in Duchenne disease is also expressed in the CNS, where its down-regulation may cause BCB alterations and it is not possible to directly link BCB alterations in Duchenne to muscular dystrophy." (PMID 38310100, 2024). "These two genes, DMD and TTN, are the most significant differentially expressed genes (DEGs) that contribute to the development of muscular dystrophy." (PMID 39415830, 2024).
muscular dystrophy (continued). "We report a novel approach to discover a class of compounds that enhance the binding of dystrophin ABD1 to actin, with the ultimate goal of developing improved therapies for muscular dystrophy patients." (PMID 36372234, 2022). "Sarcolemma stability is ensured by the dystrophin-glycoprotein complex (DGC), and several studies reported that mis-splicing of components of DGC can lead to muscular dystrophy." (PMID 34831073, 2021). "Murine primary cell cultures have been widely studied for myogenesis and muscular dystrophies in vitro analysis such as LGMDR1, LGMD2I or DMD." (PMID 32448375, 2020). "Similar changes, however, have been observed in other muscular dystrophies, such as other types of LGMD (LGMD2A, 2B and 2C) and DMD." (PMID 31430305, 2019). "We used the zebrafish model, extensively characterised and widely used for studying muscular dystrophy 10, to explore the effects of overexpressing CBP in a Dystrophin-null background." (PMID 29399383, 2017). "Since the results of comparative proteomic studies of muscular dystrophy and the determination of secondary effects downstream of dystrophin deficiency have previously been reviewed, these aspects of the proteomic analysis of the dystrophin complex will not be covered in detail." (PMID 26793286, 2016). "A previous study reported that the deletion of leucine 3238 in dystrophin Dp427 induces cognitive impairments without muscular dystrophy." (PMID 41824108, 2026). "Muscular dystrophy is a class of diseases, among which DMD is a severe, progressive disorder caused by mutations in DMD that result in the absence of functional dystrophin protein." (PMID 40695994, 2025). "A specific type of muscular dystrophy cannot be determined by the histological phenotype; thus, both cases were confirmed to have an absence of dystrophin protein on immunofluorescence staining using antibodies against dystrophy-associated proteins." (PMID 41300820, 2025). "This study identified a false positive 1 bp deletion in the DMD gene, which is responsible for muscular dystrophy, in felCat9 but not in AnAms 1.0." (PMID 39490737, 2025). "A total of 236 patients [Age range (Mean); 1.5–42 Yrs (9 Yrs); Gender (Male-233:Female-3)] exhibiting characteristic clinical findings of Muscular Dystrophy (Clinically diagnosed DMD-215, Clinically diagnosed BMD-21) were subjected to DMD gene deletion/ duplication analysis by mPCR and MLPA." (PMID 38195599, 2024). "None of the referred cases was diagnosed with a muscular dystrophy other than DMD/BMD although VUS were detected in genes of the neuromuscular panel for 22 of the 42 babies with elevated CK‐MM and no DMD pathogenic variants." (PMID 37350320, 2023). "Although dystrophin disruption leads to a fragile sarcolemma, not all muscular dystrophies arise from this mechanism." (PMID 37746696, 2023). "Subsequent genetic studies, a multiplex ligation-dependent probe amplification test and sequencing for DMD, a targeted gene panel for muscular dystrophy, and ES were conducted, but none of these tests resulted in a diagnosis." (PMID 36209187, 2022). "Thus, not only does muscular dystrophy result in defective skeletal muscle and impaired vascular function but additional symptoms such as cardiomyopathy and cognitive impairment might also suggest that dystrophin and the DAPs may be important to vascular smooth muscle." (PMID 36505053, 2022). "The absence of dystrophin has gave a massive impact on myotube development in Muscular Dystrophy pathogenesis." (PMID 34706731, 2021). "The first and most extensively used canine MD model is the golden retriever with muscular dystrophy (GRMD), which carries a splice site mutation in intron 6 that causes exon 7 skipping and a lack of dystrophin protein production." (PMID 32977524, 2020). "The deletion of Dmd exons 52-54 is predicted to disrupt the ORF leading to the lack of dystrophin expression and consequential development of a muscular dystrophy phenotype." (PMID 32988972, 2020).
muscular dystrophy (continued). "However, dystrophin is the largest human gene and DMD is the most severe and common form of muscular dystrophies in China." (PMID 30938079, 2019). "Some of the more devastating muscular dystrophies are those that develop due to the absence of components of the dystrophin-glycoprotein complex (DGC), resulting in compromised sarcolemmal integrity in skeletal muscle and the heart." (PMID 31443395, 2019). "Duchene Muscular Dystrophy (DMD) is the most frequent muscular dystrophy and one of the most severe due to the absence of the dystrophin protein." (PMID 29692797, 2018). "During muscular dystrophy, the absence of dystrophin protein severely diminishes sarcolemmal stability and hence, proteins like albumin, which are otherwise restricted to circulation, are able to cross the sarcolemma and accumulate in myofibers." (PMID 29228710, 2017). "For the patients with muscular dystrophies, the lack of dystrophin further increases intra-operative bleeding." (PMID 27928452, 2016). "The microdeletion of the short arm of chromosome X found in our patient does not include the DMD gene; therefore the features of muscular dystrophy should not appear in the future." (PMID 27656210, 2016). "A subset of congenital muscular dystrophies in humans (including MDDGA11), called dystroglycanopathies, is characterized by a reduced glycosylation of α-dystroglycan (α-DG), which is an integral component of the dystrophin glycoprotein complex." (PMID 26452345, 2015). "In particular, α1-syntrophin, interacts with dystrophin and related proteins and disruption of the dystrophin-syntrophin complex has been suggested to promote the excessive calcium influx and altered MAPK and GTPase signaling observed in muscular dystrophy." (PMID 25216282, 2014). "Patients with muscular dystrophy have little or no dystrophin, and it has been suggested that this results in the disruption of muscle membranes, which alters calcium-channel activity, thereby strongly increasing intracellular calcium concentration." (PMID 22776072, 2012). "Our results showed a lack of substitutions or indels in patient P7, who has DMD (Muscular Dystrophy, Duchenne Type)." (PMID 22216297, 2011). "The mdx muscular dystrophy is characterized by a complete absence of dystrophin that is involved in the maintenance of the morphological and functional structure of the striated, smooth and cardiac muscle fibers and in calcium homeostasis." (PMID 20105331, 2010). "The DMD pig lacking DMD exon 52, which has been developed by our group, displays a progressive and markedly accelerated muscular dystrophy, and a similar phenotype compared to the human disease with proximal muscle weakness, cardiac and respiratory involvement." (PMID 36295103, 2022). "Of note, dystrophin‐lacking skeletal muscles are characterised by significantly impaired Ca2+‐release from the sarcoplasmic reticulum in muscular dystrophy and the dystrophic phenotype of abnormal excitation–contraction coupling is exacerbated in dystrophin/utrophin double‐KO fibres." (PMID 35902360, 2022). "Increased levels of H3K56ac in muscle-specific Sirt6 mutants resulted in increased expression of Utrn, which compensates to a certain degree for the absence of dystrophin in mdx mice, thereby reducing damage of myofibers and partially ameliorating muscular dystrophy." (PMID 35859073, 2022). "In addition, absence of dystrophin in SCs reduced the commitment of MPCs by reducing asymmetric division which is thought to exacerbate impaired regeneration in muscular dystrophies." (PMID 32612995, 2020). "Since BGP-15 adjuvant therapy preserved skeletal muscle contractile function, which has previously been shown in other myopathic models, the reduction in both dystrophin and β-dystroglycan expression appears not to have the same impact on muscle function as it does in muscular dystrophy models." (PMID 33348673, 2020).
muscular dystrophy (continued). "Furthermore, we did not observe these phenotypes in the unrelated mouse muscular dystrophy mutant (mdx dystrophin mutant)." (PMID 24244862, 2013). "By comparing the histopathology of plectin/dystrophin dKO, mdx, and plectin cKO mice, it became clear that, overall, the additional lack of plectin in dKO mice was aggravating the muscular dystrophy phenotype of mdx mice, not at least because of the early death of double-deficient mice." (PMID 23758845, 2013). "A short C-terminal isoform of dystrophin (apodystrophin, Dp71 or non-muscle dystrophin) is widely distributed in various non-muscle tissues, but Dp71 is not affected in mdx and its absence does not contribute to muscular dystrophy." (PMID 19277212, 2009). "Additionally, mTOR- reduces the transcription of dystrophin, resulting in a decrease in the content of the dystrophin-glycoprotein complex (DGC), which connects the cytoskeleton of a muscle fiber to its surrounding extracellular matrix; the disruption of DGC results in muscular dystrophy." (PMID 29089899, 2017). "Fibrosis is one of the key features in several disorders including muscular dystrophies such as DMD, where the absence of dystrophin leads to degeneration/regeneration cycles of the myofibers that will eventually be replaced by connective tissue and fat." (PMID 28520806, 2017). "Intramuscular injection of donor muscle-derived cells into chimeric cxmd recipients restored dystrophin expression for at least 24 weeks in the absence of post-transplant immunosuppression, indicating that cell transplantation may be a viable therapeutic option for muscular dystrophy." (PMID 22340947, 2012). "Furthermore, some siblings (fewer than five) were observed with hospital-diagnosed muscular dystrophy (ICD-10: G71.0) at least once during the study, but not the DMD-specific ICD-10 code G71.OH." (PMID 38217608, 2024). "Consequently in some muscular dystrophies, including DMD and BMD, utrophin is present at the muscle fibre sarcolemma due to the significant regeneration taking place, in addition to the up-regulation in DMD and BMD that is present in the absence of dystrophin." (PMID 26974331, 2016).
dystrophinopathy (227 papers, 2007 to 2026). "Genetic testing was initiated, and results later identified a pathogenic X-linked deletion of exons 44-50 in the dystrophin (DMD) gene, consistent with cardiac-restricted dystrophinopathy." (PMID 42292503, 2026). "Duchenne/Becker muscular dystrophies (DMD/BMD), collectively known as dystrophinopathies, are inherited muscle disease caused by an abnormality in the DMD gene that encodes the dystrophin protein." (PMID 40703779, 2025). "The DMD gene is prone to de novo mutations, resulting in a group of neuromuscular disorders collectively known as dystrophinopathies." (PMID 39673425, 2025). "In conclusion, we discovered various new factors that are subject to regulation by dystrophin deficiency on a protein level, and our data further reiterated the high degree of proteome alterations in dystrophin-mutated individuals." (PMID 40558519, 2025). "We searched PubMed for articles published in English from 1 January 1994 to 1 January 2024, using the search terms ‘dystrophin’, ‘Duchenne’, ‘dystrophinopathy’, ‘interactors’, ‘mdx’ or the causative gene, ‘DMD’, and ‘brain’." (PMID 39673425, 2025). "This study concludes the first integrated genomic and statistical-genetics analysis of DMD mutations in a Kazakh cohort, revealing a mutational landscape that aligns with global patterns of dystrophinopathy while displaying distinct regional features." (PMID 41595440, 2025). "Dystrophinopathies are neuromuscular disorders caused by the absence/reduction of dystrophin function, a product of the DMD gene located on Xp21." (PMID 40451248, 2025). "The expanding spectrum of deep intronic mutations in the DMD gene underscores the necessity of integrating advanced genomic and transcriptomic approaches to resolve the molecular complexity of dystrophinopathies." (PMID 41321997, 2025). "Most pathogenic variants clustered within the well-established DMD mutational hotspot spanning exons 45–55, consistent with global dystrophinopathy datasets." (PMID 41595440, 2025). "Our study is the second report of aberrant splicing induced by DMD missense variants in dystrophinopathies, which contributes to the clinical and genetic interpretation of uncertain DMD missense variants." (PMID 38486238, 2024). "Despite the asymptomatic course in most women with the DMD mutation and symptoms in up to about a third of those with dystrophinopathy, cases of heart transplantation and cardiac death have been described." (PMID 39075955, 2024). "These dystrophinopathies are caused by mutations in the dystrophin gene (DMD) that can be either spontaneous or inherited." (PMID 38501170, 2024). "Dystrophinopathies are X-linked recessive disorders caused by mutations in the dystrophin gene (Xp21), encoding for the sarcolemma protein dystrophin virtually present in all tissues, but mostly in skeletal muscle cells and cardiomyocytes." (PMID 38610600, 2024). "The genetic spectrum of dystrophinopathies consists of both coding and non-coding DMD variants, ranging from single nucleotide variants (SNVs) to complex structural variants." (PMID 38486238, 2024). "Pathogenic missense variants in the dystrophin (DMD) gene are rarely reported in dystrophinopathies." (PMID 38486238, 2024). "Genetic diagnosis of dystrophinopathies can be sometimes challenging due to the existence of atypical pathogenic DMD variants." (PMID 38486238, 2024). "Dystrophinopathies are X-linked muscle disorders resulting from mutations in the dystrophin gene (Xp21), causing abnormalities in the dystrophin protein crucial for maintaining muscle cell membrane integrity during contraction." (PMID 39777119, 2024). "Collectively, the pathological analyses indicated that DMD-edited microminipigs displayed characteristic phenotypes of DMD associated with dystrophin deficiency." (PMID 38702481, 2024). "Dystrophinopathies are caused by mutations in DMD gene, the largest known human gene, covering 2.4 megabases (0.08% of the human genome) at locus Xp21." (PMID 38791328, 2024).